IGF1 (insulin like growth factor 1)
Diseases named in the same sentence as IGF1 in open-access papers (continued):
Sharing a sentence is not in itself a finding about the gene and the disease.
atherosclerosis (continued). "In particular, some adverse effects of this claimed “elixir of youth” for elderly people, including atherosclerosis, osteoarthrosis, and tumours, might depend upon IGF-1 (deleterious as endowed with pro-ageing effects) rather than upon GH (beneficial as endowed with anti-ageing effects)." (PMID 40507601, 2025). "PAPP-A functions as a protease for insulin-like growth factor-binding proteins (IGFBPs) and it was postulated that PAPP-A’s role in enhancing the local availability of insulin-like growth factor 1 (IGF-1) may potentially expedite the progression of atherosclerosis." (PMID 39351476, 2024). "GH and IGF-1 may also protect peripheral vasculature from atherosclerosis." (PMID 34713389, 2022). "Therefore, we determined whether IGF-1 mimetic peptides could inhibit the inflammatory response during the development of atherosclerosis." (PMID 32929345, 2020). "Thus, increasing IGF-1 level in circulation might serve as a promising therapeutic approach for atherosclerosis treatment." (PMID 32929345, 2020). "MMP8 is expressed by many plaque cell types, but as macrophages are the major source of MMP in atherosclerosis, we first wanted to investigate the role of MMP8 derived from macrophages and how IGF-1 influences MF phenotype." (PMID 40991633, 2025). "Excess visceral fat promotes tumorigenesis through increased insulin-like growth factor-1 (IGF-1) signaling and pro-inflammatory cytokines (IL-6, TNF-α), while also accelerating atherosclerosis and heart failure." (PMID 40227756, 2025). "We reported recently that MF-specific IGF-1 overexpression decreases CXCL12 plaque and circulating levels and promotes atherosclerosis in mice." (PMID 36602878, 2023). "Chronic WBV increased IGF-1 levels further in CRS rats, but decreased in mice models with atherosclerosis." (PMID 36009865, 2022). "Taken together, IGF-1 mimetic peptide reduces the macrophage and VSMC-derived foam cells, which contributes to the inhibition of atherosclerosis." (PMID 32929345, 2020). "Growth factors such as bFGF, EGF, IGF-1, PDGFB, TGF-β1 and VEGF-A play important roles in VSMC and EC migration and proliferation, therefore playing important roles in the pathogenesis of atherosclerosis." (PMID 27835972, 2016). "Systemic MMP8 deficiency decreased atherosclerosis in non-irradiated MMP8KO/ Apoe-/- mice and IGF-1 administration reduced atherosclerotic burden in Apoe-/- mice." (PMID 40991633, 2025). "Similarly, insulin-like growth factor-1 (IGF-1) expressed in atheroma bound with αVβ3 integrins activated the PI3 kinase/PKC/p38 signaling pathway, an essential step in the progression of atherosclerosis." (PMID 37047140, 2023). "Interestingly, IGF-1 is not only found in the circulation but also in arteries, with studies having reported IGF-1 to exert cardioprotective effects in the setting of atherosclerosis." (PMID 36970368, 2023). "Recent studies indicate that IGF-1 exerted both pleiotropic antioxidant effects and anti-inflammatory effects, which reduced atherosclerotic burden, while losing IGF1R on smooth muscle promoted atherosclerosis." (PMID 35882857, 2022). "The IGF-1 deficit was not sufficient to induce systemic inflammation, atherosclerosis, or alterations in blood pressure, likely due to the relatively short observation time." (PMID 33807089, 2021). "In addition, smooth muscle cell (SMC) proliferation in atherosclerosis was found to mediate through the interaction of growth factors like platelet-derived growth factor-RB (PDGF-RB) and insulin-like growth factor-1 (IGF-1) and their receptors (R)." (PMID 22761820, 2012). "ST analysis revealed that IGF‐1 inhibited gene expression of FOS/FOSB factors, as well as MMP9 and CXCL14 in plaque macrophages, these molecules may be involved in the IGF‐1 effect on atherosclerosis." (PMID 40156163, 2025).
atherosclerosis (continued). "In ApoE knockout models, supplementation of a stable IGF-1 analog stabilized plaque development by increasing vascular smooth muscle (VSMC) cell proliferation, suppressing inflammation-induced VSMC apoptosis, and increasing the cap to core ratio in early atherosclerosis." (PMID 36755922, 2023). "It has been proposed that IGF-1 may protect against atherosclerosis (as opposed to the opposite pro-atherosclerotic effects of oxidative stress and inflammation) and increase the production of NO and NOS in endothelial cells." (PMID 33989340, 2021). "Additionally, it has been established that IGF-1 plays a crucial role in maintaining the homeostasis of cardiac physiology, and negative alterations in IGF-1 levels can lead to cardiac complications such as atherosclerosis, inflammation, vasodilation, cardiac apoptosis, and autophagy." (PMID 38531890, 2024). "Corresponding to the adverse changes in IGF-1 within the heart, negative changes in PI3K and AKT can also lead to atherosclerosis in the heart." (PMID 38531890, 2024). "The negative changes of IGF-1 in T2DM can lead to CVD problems through two perspectives, namely atherosclerosis, inflammation, vasodilation, cardiac apoptosis, and autophagy, and by affecting the PI3K/Akt cascade." (PMID 38531890, 2024).
melanoma (114 papers, 2008 to 2025). A malignant, usually aggressive tumor composed of atypical, neoplastic melanocytes. "IGF-1 (insulin-like growth factor) is a growth factor closely associated with insulin, which has been found to mediate resistance to anoikis in melanoma cells." (PMID 38460046, 2024). "We found that NECTIN1 loss changes the response of melanoma cells to microenvironmental insulin-like growth factor 1 (IGF1) signaling by controlling a switch from cell–cell adhesion to cell–matrix adhesion." (PMID 36229674, 2022). "We found that NECTIN1 loss stimulates melanoma cell migration in vitro and spreading in vivo in both zebrafish and human tumors specifically in response to decreased IGF1 signaling." (PMID 36229674, 2022). "Another study has shown that the expression of FGF2 by human melanoma cells mediated the promotion of tumor-associated B cells to express IGF1." (PMID 34830951, 2021). "For rs1520220/IGF1 in the recessive model, men with GG genotype showed extremely high risk of melanoma (OR 8.11, 95% CI: 2.20, 52.50, p = 0.006) while women with GG genotype showed a significant lower risk (OR 0.15, 95% CI: 0.018, 0.86, p = 0.045)." (PMID 32150843, 2020). "The GG phenotype in IGF1 rs1520220 (recessive model) presented an increased risk of melanoma (OR = 8.11, 95% CI: 2.20, 52.5, p = 0.006) in men but a significant opposite effect in women (OR = 0.15, 95% CI: 0.018, 0.86, p = 0.045)." (PMID 32150843, 2020). "Three SNPs (rs12662670 and rs2234693 from ESR1 and rs5742694 from IGF1) were thus excluded for further analyses, even though their χ2 statistics showed significant association with melanoma risk." (PMID 32150843, 2020). "Treatment of GCNT2 KD, GCNT2 OE and control melanoma cell variants with IGF-1, the cognate ligand for IGF1R, revealed that low GCNT2/I-branched glycan levels increased melanoma cell proliferation." (PMID 30135430, 2018). "One factor produced by melanoma cells and their microenvironment, insulin-like growth factor-1 (IGF- 1), is linked to epithelial-mesenchymal transition (EMT) and stemness features in several cancers." (PMID 27764776, 2016). "We observed a signature biomarker change in the serum associated with EE-induced inhibition of melanoma including decreased leptin, increased adiponectin, and decreased IGF-1." (PMID 24587106, 2014). "In particular, for malignant melanoma, the strong size effect on cancer incidence is hypothesized to be caused by the higher cell division rate and increased IGF-1 levels." (PMID 36066621, 2023). "A positive association was observed between serum IGF-1 level and overall cancer risk in men in the United Kingdom (hazard ratio [HR] = 1.03 per 5-nmol/L increment in IGF-1) and specific cancer risk, such as prostate, melanoma, kidney, and thyroid (HR = 1.09, 1.08, 1.10, and 1.22, respectively)." (PMID 35370981, 2022). "Moreover, forced IGF1 signaling partially reversed the migratory propensity of NECTIN1-deficient cells in the modified transwell assay in 6 different human melanoma cell lines, similar to direct treatment with IGF1 itself." (PMID 36229674, 2022). "Of these studies, none have been addressed in melanoma, and hence, the actual causal mechanism of IGF1 rs1520220 in melanoma remains unclear." (PMID 32150843, 2020). "In summary, our data might suggest that the G allele in IGF1 rs1520220 is likely to be associated with melanoma risk, while the A allele in IGF1R rs2229765 may have a protective effect, especially in men, in recessive genetic models." (PMID 32150843, 2020). "Our current results also showed an increased risk of melanoma by IGF1 rs1520220 C alleles." (PMID 32150843, 2020). "Also, TCGA data set analyses confirm the co-expression of IGF-1 with B-cell genes in melanoma biopsies and higher IGF-1 level to be associated with an enhanced frequency of TAB cells." (PMID 28928360, 2017). "However, little is known about the molecular mechanisms underlying IGF-1-mediated metastatic potential in melanoma." (PMID 27764776, 2016).
melanoma (continued). "BRAF inhibitor resistance could be caused by HGF-triggered MET activation, and IGF-1 triggered its receptor activation in BRAF mutant melanoma." (PMID 24952482, 2014). "Indeed, the molecular mechanisms underlying IGF-1-mediated stemness remain largely unknown in melanoma." (PMID 27764776, 2016). "The incidence of melanoma is higher in individuals with elevated serum insulin-like growth factor-1 (IGF1) concentrations." (PMID 40732958, 2025). "Based on our findings, we propose that combining anti-PD-L1 therapy with either AKT inhibition or IGF-1 pathway inhibition represents a promising therapeutic strategy for melanoma." (PMID 41429766, 2025). "Since only melanoma cells express the receptor for IGF-1, B16-F10 cells were treated with IFN-γ alone or in combination with IGF-1." (PMID 41429766, 2025). "In the international Genes, Environment, and Melanoma study (GEM) dataset, the variants of rs1520220 in IGF1 and rs2229765 in IGF1R were significantly related to CM risk, but not in the Gene Environment Association Studies Initiative (GENEVA) dataset." (PMID 38892441, 2024). "Studies focusing on melanoma have shown that B-cell infiltration in the TME results in the secretion of insulin-like growth factor 1 (IGF1), which promotes drug resistance to BRAF and MEK inhibitors." (PMID 36945046, 2023). "The melanoma pathway showed the highest enrichment in both the AngII and IGF-1 groups [p = 0.003 with 8.35-fold enrichment, and p = 0.004 with 7.57-fold enrichment, respectively]." (PMID 37829282, 2023). "Downregulation of lncRNA H19, which regulates the miR-18b/IGF1 axis, is said to make melanoma cells more sensitive to the effects of DDP, which is in agreement with our findings." (PMID 37361693, 2023). "At the same time, IGF-1 was found to contribute to the expansion of melanoma-initiating cells through an epithelial-mesenchymal transition process." (PMID 37047539, 2023). "Possibly, insulin-like growth factor 1 (IGF1) also contributes to the resistance of melanoma cells to BRAF inhibitors." (PMID 35565444, 2022). "Our data show that NECTIN1 status determines the response of melanoma cells to environmental stress, specifically a drop in local IGF1 concentration." (PMID 36229674, 2022). "Upregulation of genes involved in macrophage recruitment (Ccl2), cell adhesion and migration (Vcam1, Stab1, Lyve1), angiogenesis (Vegfa) and cell proliferation/survival (Igf1) all suggested a phenotype similar to TAMs of s.c. melanoma." (PMID 36241867, 2022). "We performed immunofluorescence in tissue sections of 20 human melanoma biopsies with markers of active IGF1 signaling (phospho-IGF1R) and adherens junctions (α-catenin) and independently evaluated NECTIN1 expression." (PMID 36229674, 2022). "We therefore assessed the interaction between IGF1 signaling and adherens junctions in human melanoma in vivo." (PMID 36229674, 2022). "For instance, H19 silencing has enhanced the sensitivity of cancer cells to cisplatin and increased apoptosis of cisplatin-resistant melanoma cells through modulation of IGF1 expression." (PMID 33768092, 2021). "IGF-1 increases the survival, growth, and migration of melanoma cells from early tumor lesions by activating MAPK and AKT signalling pathways." (PMID 34067929, 2021). "Blocking IL-8 signalling in melanoma cells was shown to abrogate IGF-1-induced melanoma cell migration." (PMID 34067929, 2021). "In particular, upon activation by melanoma cells, fibroblasts were shown to produce growth factors like insulin-like growth factor-1 (IGF-1) and HGF." (PMID 34067929, 2021). "In line with this notion, it has been established that IGF-1 (insulin-like growth factor 1) plays a key role in inducing resistance to apoptosis in melanoma cells." (PMID 34207884, 2021). "Later, a study indicated implication of IGF-1 in melanoma pathophysiology through activation of anti-apoptotic proteins Bcl-2 and Bcl-XL and surviving." (PMID 33918490, 2021).
melanoma (continued). "H19 via acting as a molecular sponge of miR-18b can regulate IGF-1 expression and sensitivity of melanoma cells to DDP." (PMID 33768092, 2021). "Here, we confirmed that both GH and IGF-1 have independent as well as overlapping actions in the intrinsic therapy refractoriness of melanoma." (PMID 33291663, 2020). "To assess effects of IGF-1 responsivity in determining patient survival, we conducted a similar comparison between melanoma patients within the top and bottom quartiles for IGF-1R expression levels and obtained similar results." (PMID 33291663, 2020). "In melanoma, IGF1 inhibition prevented malignant cell proliferation, migration and invasion, and lung colony formation in immunodeficient mice." (PMID 32851683, 2020). "Lastly, the GEM cohort was stratified by gender and logistic regression analyses were performed to measure the associations of rs1520220/IGF1 and rs2229765/IGF1R and melanoma risk in men and women, respectively." (PMID 32150843, 2020). "These syngeneic mouse melanoma models of differential GH/IGF action can be valuable tools in screening for therapeutic options where lowering GH/IGF-1 action is important." (PMID 33291663, 2020). "This factor is crucial for melanoma resistance to BRAF and MEK inhibitors, which is associated with increased levels of CD20 and IGF-1 mRNA in tumors and IGF-1 expression in tumor-associated B lymphocytes." (PMID 33171792, 2020). "Results derived from these mice, when compared to their WT counterparts with physiological levels of GH and IGF-1, allow us to tease out the independent or perhaps synergistic effect of GH and IGF-1 on the inoculated mouse melanomas." (PMID 33291663, 2020). "As an extension of our in vitro studies, we sought to study the effects of GH/IGF-1 on melanoma progression in vivo." (PMID 33291663, 2020). "We identified that GH upregulates key mechanisms of therapy resistance and metastases in melanoma tumors in an IGF-1 dependent and independent manner by upregulating multidrug efflux pumps and EMT transcription factors." (PMID 33291663, 2020). "IGF1R rs2229765 (p = 0.004) and IGF1 rs1520220 (p = 0.005) showed significant genotypic and recessive differences between melanoma cases and healthy controls." (PMID 32150843, 2020). "It has been reported that NT157 inhibits proliferation in the RAF inhibitor resistant melanoma cell line A375, both through reduced IGF1-signaling and reduced STAT3-signaling." (PMID 32667922, 2020). "The rs1520220 in IGF1 and rs2229765 in IGF1R variants were significantly associated with melanoma risk in the GEM dataset after Benjamini-Hochberg multiple comparison correction, although they were not validated in the GENEVA set." (PMID 32150843, 2020). "The IGF1 rs1520220 and IGF1R rs2229765 SNPs were thus further analyzed in the logistic regression models to determine the odds ratio (OR) of melanoma in individuals carrying minor alleles/genotypes in comparison with the reference alleles/genotypes." (PMID 32150843, 2020). "The aim of our study was to characterize the effects of GH and its downstream effector insulin-like growth factor 1 (IGF-1) on melanoma using in vitro and in vivo models." (PMID 33291663, 2020). "Perhaps the indirect effect of IGF1 is playing a role in gender disparities in melanoma, which awaits further laboratory studies to reveal any gender-specific crosstalk between IGF1 rs1520220 and sex hormones in melanoma." (PMID 32150843, 2020). "It was obvious that IGF-1 attenuated the function of Polyphyllin I in promoting melanoma cell apoptosis and autophagy." (PMID 32733943, 2020). "The ability of IGF-1 to enhance metastasis of melanoma cells through upregulation of EMT has also been reported." (PMID 33291663, 2020). "Tumor-associated B cells have even been proposed to promote resistance to BRAF and MEK inhibitors in melanoma through secretion of IGF-1 and clinical trials evaluating therapeutic B cell depletion in this context are underway (NCT01376713)." (PMID 31200747, 2019).